LINC00377 (long independently transcribed non-coding RNA 377)
Synonyms: TCONS_00021861
Gene: Long non-coding RNA gene on chromosome 13 (81,018,176 to 81,044,691, forward strand). Ensembl gene ENSG00000229246.
Diseases named in the same sentence as LINC00377 in open-access papers:
LINC00377 is named in the same sentence as 2 diseases in open-access papers, as found by Europe PMC text mining. Sharing a sentence is not in itself a finding about the gene and the disease. The quoted sentences say what the papers report.
cancer (1 paper, 2019). A tumor composed of atypical neoplastic, often pleomorphic cells that invade other tissues. "So far, no studies have reported any association between LINC00377, LINC00536, LINC01224, and LINC02037, and cancer." (PMID 31850229, 2019).
LINC00377 also shares sentences with these, for which no sentence is quoted: breast carcinoma (1 paper).